CD4 (CD4 molecule)
Diseases named in the same sentence as CD4 in open-access papers (continued):
Sharing a sentence is not in itself a finding about the gene and the disease.
tumor (continued). "The proportion of CD4+ cells displaying regulatory T cells characteristics, as evaluated by the expression of CD25 and FoxP3, was significantly lower in the tumor lysates from VV-FCU1-treated animals in comparison to that of controls." (PMID 27057460, 2016). "Preclinical data demonstrate that treatment with agonist anti-OX40 monoclonal antibodies (aOX40) induced tumor regression by boosting effector CD8 and CD4 T cell expansion and function." (PMID 27330804, 2016). "Use of the anti-Nrp-1 antibody resulted in a significantly augmented number of CD4+TGF-β1+ Th3 cells in the TDLN and tumor tissue and tumor-derived TGF-β1-producing Treg cells from IL10−/− B16/F10 and WT B16/F10 mice." (PMID 27075020, 2016). "Using cellular depletion studies we next determined the relative contribution of CD4+, CD8+ lymphocytes and NK/NKT-cells to tumor control following combined DSR-29133/RT therapy in the CT26 model." (PMID 26959743, 2016). "Consistent with our previous findings, VNP20009 treatment significantly increased the number of CD4+, CD8+, F4/80+ and Gr-1+ cells in the tumor." (PMID 27412722, 2016). "Theco-inhibitory activity is mainly mediated through the receptor PD-1 expressed onactivated CD4+ and CD8+ T cells, B cells, Tregs, natural killercells, and other tumor-infiltrating lymphocytes." (PMID 27332773, 2016). "Coadministration of a lentiviral vector vaccine with GLA-AF induced robust CD4 and CD8 T cells that reduced tumor growth and mortality in a mouse cancer model." (PMID 27466350, 2016). "Given the dependence of CY+TLRa treatment upon CD4+ and CD8+ T-cells as well as the requirement for IFNγ-producing T-cells for sustained tumor eradication, we inspected peripheral lymphoid organs for the presence of 4T1-specific T-cells." (PMID 27341020, 2016). "The results show that INFα-2b inhibits cancer cell immune evasion by decreasing the levels of CD4+CD25+Foxp3+ Tregs and suppressing the expression of TGFβ and IL-10 in the tumor microenvironment." (PMID 27389040, 2016). "Phenotypic profiling of FNA from three NSCLC samples for which we had complete flow annotation also exhibited consistency for CD4+ and CD8+ T cell suppressed markers when compared to bulk tumor." (PMID 27539742, 2016). "The results for the combined image confirmed that the CD4+ CD8+ cells all expressed FOXP3; in addition it was noted that many CD4−CD8− tumour cells were also FOXP3 positive [in agreement with the extensive staining seen in fixed tissues]." (PMID 27160146, 2016). "Overproduction of TGF-β1 in 4T1/TGF-β1 tumor-bearing mice was associated with a higher percentage of CD4+CD25+Foxp3+ cells in the lungs and CD103+CD4+Foxp3+ cells in the spleens, compared with 4T1/RFP tumor-bearing mice and tumor-free mice." (PMID 27036297, 2016). "While Th1 CD4+ T cells facilitate tumor rejection by assisting the function of cytotoxic CD8+ T cells, Th2 CD4+ T cells promote antibody production of B cells by secreting cytokines." (PMID 27044404, 2016). "Patients’ tumors were classified as being weakly to strongly infiltrated by CD4+ and CD8+ immune cells in tumor and tumor-near stroma compartments according to the median calculated for each marker." (PMID 27463005, 2016). "The higher Treg levels in tumour tissues indicated a worse prognosis and the FOXP3+ Tregs/CD4+ T cell ratio was an independent prognostic factor for OS." (PMID 27725696, 2016). "Using this approach, we confirmed and quantitated the presence of CD19+ B cells as well as CD4+, CD8+ T cells in the tumour at the end of the experiment." (PMID 27427766, 2016). "Tumor-infiltrating T lymphocytes, including CD8+ and CD4+ T cells, are considered to be a manifestation of the host immune response in ESCC." (PMID 27050369, 2016). "To investigate which T cell subset (including CD4 and CD8 cells) contributed to the anti-tumor immunity, we used anti-CD4 (rlipo-OVA/CD4), anti-CD8 (rlipo-OVA/CD8) and control antibodies (rlipo-OVA/rat IgG) to deplete subsets of T cells." (PMID 27127171, 2016).
tumor (continued). "In another model of tumour-bearing mice, we previously showed that elimination of CD25+Treg resulted in the strong activation/amplification of CD4 and CD8 effector T cells and the control of tumour growth." (PMID 27341421, 2016). "Recently, isolated metabolically active subsets of CD4+ and CD8+ T cells based on their mitochondrial membrane demonstrated increased in vivo persistence and anti-tumor activity." (PMID 26999211, 2016). "Populations of CD4+ T helper (Th) cell subsets and antigen specific CD8+ T cell subsets were determined in the tumor draining lymph node (TDLN) and tumor microenvironment (TM)." (PMID 27853305, 2016). "Next we confirmed the role of CD4+ and CD8+ T cells in anti-PD-1 and anti-CTLA-4 treatment of MC38 tumor-bearing mice." (PMID 27610613, 2016). "Interestingly, CD4+ lymphocytes in the stroma only, and not in intratumoral sites, were associated with death, emphasizing the importance of assessing the location of TILs within the tumor microenvironment." (PMID 26871598, 2016). "The proportion of CD4+ cells that secrete TNF-α and IFN-γ upon stimulation decreased after radiation in both tumours suggesting a decreased TH-1 response." (PMID 28008921, 2016). "The cryo-thermal therapy decreased the immune suppression cells (MDSCs) greatly to relieve the immune suppression, and increased CD4+, CD8+ T lymphocytes to trigger specific strong anti-tumor immunity leading to long term survival of the treated mice." (PMID 27256519, 2016). "Again, antigen presentation was enhanced for both anti-tumor antibody production and generation of MUC1-reactive CD4+ T cells." (PMID 27472370, 2016). "PD1, TIM3, BTLA, 2B4, LAG3 were markedly increased in both CD4+ and CD8+ T cells of B16F10 tumor-bearing mice compared to naive mice." (PMID 27447564, 2016). "Animal from CHOP×2 group showed significantly higher numbers of CD4+ (p = 0.0023) and CD8+ (p = 0.0034) tumor-infiltrating T cells as compared with animals from the control group." (PMID 27876058, 2016). "Further, Cxcl14 reexpression significantly increases natural killer (NK), CD4+ T, and CD8+ T cell infiltration into the tumor-draining lymph nodes in vivo." (PMID 27143385, 2016). "Splenic CD11b+Gr-1+ cells from 4T1-bearing mice were confirmed to exhibit prototypical MDSC suppressor function defined by potent inhibition of CD3/CD28-driven proliferation of CD4+ and CD8+ T cells (from non-tumor bearing mice) in vitro." (PMID 27929373, 2016). "CD69+ cells were increased in the tumor cell area in CD4+ and CD8+ T-cells, while FoxP3+CD25+CD4+ Tregs and CD25+CD8+ T-cells were significantly increased outside the tumor area." (PMID 27999289, 2016). "We then examined Tim‐3 on peripheral CD4+ and CD8+ T cells in patients with different primary tumor locations." (PMID 27516959, 2016). "Immunization against the BCL1-specific antigen preserved the levels of CD4+, CD8+, and Treg T cell subsets even after tumor challenge." (PMID 27959896, 2016). "In the setting of cancer, MHC molecules play the pivotal role of presenting processed tumor antigens to CD4 and CD8 lymphocytes in order to generate a tumor-specific cytotoxic response." (PMID 27729860, 2016). "Furthermore, we found higher frequencies of Tregs in tumor associated lymphocytes in non-miliary, as opposed to ascites, although only small numbers of CD4+ positive cells were observed within tissue samples (i.e. median of 7.7% versus median of 48% of lymphocytes in blood, respectively)." (PMID 27665539, 2016). "PD-1+CD4+ and CD69+ T-cells were located inside, and Tregs and CD25+CD8+ cells outside the tumor cell area." (PMID 27999289, 2016). "In ovarian cancer, hypoxia induces angiogenesis in humans and mice, where CD4+, CD25+ and tumour-infiltrating regulatory T cells secrete high quantities of VEGFA and promote the dissemination of endothelial cells, both ‘in vitro’ and ‘in vivo’." (PMID 26913068, 2016).
tumor (continued). "TGF-βs are also known to stimulate the conversion of CD4+CD25- T cells to CD4+CD25+Foxp3+ regulatory T-cells, which inhibit anti-tumor immunity." (PMID 27863384, 2016). "Treatment of ascophyllan led to substantial increases in the proportions of IFN-γ- and TNF-α-producing CD4 and CD8 T cells in the spleen and tumor drLN, whereas IL-4- or IL-17-producing CD4 and CD8 T cells were not increased by ascophyllan treatment." (PMID 27008707, 2016). "While α-CTLA-4 or α-PD-1 monotherapy induced CD4+ and CD8+ T-cell infiltration into tumours, combination therapy resulted in markedly greater infiltration of both." (PMID 27498556, 2016). "First, we analysed the levels of CD4+ and CD8+ T cells in the blood, spleen and tumour tissues from different mice groups." (PMID 27074905, 2016). "This would also allow for more complete evaluation of the TIL compartment, including CD4+ TIL, which have been previously demonstrated to recognize autologous tumor." (PMID 27777771, 2016). "In contrast, both the CD4+ and CD8+ T cells in the spleens of mice with dormant tumor remained stable." (PMID 27959896, 2016). "Selective expansion of CD8+ T cells in the mini-REP prevented their dilution by CD4+ T cells, and allowed an increased opportunity to capture CD8+ T cell tumor reactivity through a co-culture assay." (PMID 27777771, 2016). "Binding of CD40 on CD4+ T cells to its respective ligand, CD40L, found on tumors leads to cytotoxic T cell recruitment and elicits an anti-tumor effector response." (PMID 27854240, 2016). "The parallel presentation of antigens to both CD4+ and CD8+ T-cells allows to generate strong primary immune responses to prevent tumour escape." (PMID 26795765, 2016). "The differences in the presence of CD4+, CD8+, and CD20+ TILs in pT1–pT2 vs. pT3–pT4 tumors suggest that the immune response depends on the stage of tumor development, being less effective in more advanced tumors." (PMID 26927070, 2016). "Following a response to MAPK pathway inhibition, there is an increase in PD-L1 expression on tumor cells and a higher lymphocytic infiltration (CD8/CD4), as well as, a decrease in Treg infiltration and immunosuppressive cytokines (IL6, IL10, VEGF)." (PMID 27447748, 2016). "LP cells in NLPHL are surrounded by PD-1+CD4+ and CD69+CD4+ cells with a TEM phenotype, while levels of Tregs and CD25+CD8+ cells are increased outside the tumor cell area." (PMID 27999289, 2016). "We analyzed the infiltration of helper T cells (CD3+CD4+), cytotoxic T cells (CD3+CD8+), and NK cells (CD3−NKp46+) in tumor tissue and the population of these cells in spleen by flow cytometry." (PMID 27034590, 2016). "Tumor-infiltrating CD8+ T cells, CD4+ T cells and natural killer (NK) cells were analyzed by flow cytometry." (PMID 27178315, 2016). "Both naringenin and 1D11 treatments significantly reduced the percentage of CD4+CD25+Foxp3+ and CD103+CD4+Foxp3+ cells in the lungs and spleens, respectively, of 4T1/TGF-β1 tumor-bearing mice (P <0.05)." (PMID 27036297, 2016). "The number of CD4+, CD8+, CD25+, FoxP3+ and CD20+ TILs in the late phase of tumor development (pT3–pT4) was significantly lower compared to that observed for less advanced tumors (pT1–pT2)." (PMID 26927070, 2016). "CD4+ T cells enhanced the clonal expansion of CD8+ T cells in secondary lymphoid tissue after vaccination and tumor-specific CD4+ also facilitated recruitment, proliferation, and effector function of CD8+ into the TME by secretion of IFN-γ and IL-2." (PMID 26980946, 2016). "Regulatory T cells (Tregs), particularly CD4+CD25+Foxp3+ Tregs, down regulate immunity and promote tumor cell growth." (PMID 27389040, 2016). "Regulatory T cells (Tregs), particularly the CD4+CD25+Foxp3+ Tregs, down regulate immunity and promote tumor cell growth by directly suppressing CD8+ and CD4+ T cells." (PMID 27389040, 2016).
tumor (continued). "Immunohistochemical staining revealed that tumor samples taken at baseline before treatment had variable numbers of CD3+ cells, CD8+ cells, CD4+ cells, CD68+ cells, CD163+ cells, and CD11c + cells." (PMID 26981247, 2016). "Such in vivo immune modulation by curcumin led to enhanced IFNγ+ CD4 and CD8 T cells with heightened capacity to lyse syngeneic 4T1 tumor cells, resulting in inhibition of tumor growth." (PMID 27405665, 2016). "ACT with tumor-infiltrating lymphocytes (TILs) is an approach where T cells, generally mixtures of CD8+ and CD4+ T cells grown from resected metastatic tumor deposits, are harvested and expanded ex vivo prior to adoptive transfer." (PMID 27151159, 2016). "Thirdly, in addition to such MDSC-‘re-educating’ effects, both cationic polymers directly decreased the number of MDSCs and, in contrast, increased that of both CD4+ T and CD8+ T cells in the blood, spleen and the tumour tissues." (PMID 27074905, 2016). "Treatment significantly reduced CD4+CD25hiFoxp3+ regulatory and PD-1+ (exhausted) CD4+ and CD8+ T cells and decreased CD45RO-CD62L+ (naive) T cells, consistent with improved anti-tumor immunity." (PMID 27463016, 2016). "In this tumor, a large number of CD20+ cells were still present, and only a small number of CD3+, CD4+ and CD8+ T cells were present by immunohistochemistry." (PMID 29263894, 2016). "In this study, we have developed an in vitro cell expansion method to generate Th1-like cells from naive CD4+ Th cells, and demonstrated their ability to produce multiple Th1-cytokines, cytotoxicity and enhance CD8+ CTL-mediated tumor rejection." (PMID 27588200, 2016). "The immune cells recruited to the tumor included cells expressing markers CD68, CD163, CD4, and CD25." (PMID 26964534, 2016). "From our study, it is apparent that the percentage level of the CD4+ and CD8+ T lymphocytes were dropped in the tumor group when compared to the normal group." (PMID 27558166, 2016). "In cancer, adaptive immune cells such as CD4+ T helper cells and CD8+ T cells are activated through presentation of tumor antigen in Major Histocompatibility Complex (MHC)-Class II and Class I by antigen presenting cells, respectively." (PMID 27853305, 2016). "The increased percentages of TEM and PD-1+CD4+ cells in NLPHL, combined with the increased numbers of CD69+ cells in the tumor cell area, suggests that egress of these cells from the tumor cell area is inhibited." (PMID 27999289, 2016). "Measurement of CD4+ and CD8+ T lymphocytes in serum from orthotopic transplantation mice at 3 weeks after implantation revealed a decreased ratio of CD4+/CD8+ T lymphocytes compared to normal C57BL6 mice, an indicator for the extent of tumor progression." (PMID 26824903, 2016). "Synthetic long peptides (SLPs) are processing-dependent linear amino acid sequences harboring multiple potential CD4+ and CD8+ T cell epitopes that are expressed by tumor cells." (PMID 27564262, 2016). "Antigen-only, irrelevant-antigen, and chemokine-fusion vaccines elicit significantly higher and similar CD4+ and CD8+ tumor-infiltrating lymphocyte (TIL) levels compared to mock vaccine." (PMID 28018602, 2016). "Regulatory T cells (Tregs, CD4+CD25+FoxP3+) stimulate immune tolerance and facilitate tumor progression." (PMID 26862849, 2016). "In this study, we compared tumor-infiltrating CD3+, CD4+, CD8+ T-cells, and granzyme inhibitors (SERPINB1, SERPINB4, and SERPINB9) between HPV-positive and HPV-negative tumors and the relation with survival." (PMID 26993499, 2016). "Although the tumour sizes were markedly different, the percentages and phenotype of CD4+ and CD8+T cells within the tumour mass were similar." (PMID 26831747, 2016). "Early studies generally focused on direct tumor recognition by CD8+ T cells, while more recently developed models have employed CD4+ T cells." (PMID 27121060, 2016). "Further studies are required to confirm the exact role of CD4+ and CD8+ T cells in the control of MDV replication and tumour growth." (PMID 27894330, 2016).
tumor (continued). "Immunohistochemically there was an expression of histiocytic markers (CD4, CD68) as well as smooth muscle cell markers (SMA, H-Caldesmon) in the tumor cells." (PMID 28018701, 2016). "Our results demonstrated that the Treg (CD4+CD25+FoxP3+) cell population was significantly decreased in the spleen and also in the tumor of the BME-fed mice as compared to control animals, suggesting the immunomodulatory role of BME." (PMID 27120805, 2016). "Our data provide a possible explanation by showing that the infusion product obtained after expansion is likely reduced in the intraepithelial (tumor-reactive) CD103+ TIL population and predominantly comprised of CD4+ and stromal CD8+ T cells." (PMID 27650547, 2016). "In contrast, CD8 T cells undergo divisions in the presence of tumour DCs from treated mice, these divisions being potentiated by addition of anti-CD3 mAbs and even more by addition of CD4 T cells in the cultures." (PMID 27341421, 2016). "CD4+ and CD8+ cells were detected in all assessable samples, although in 13 (15.5%) of the 84 samples CD4+ cells were only found in the tumor-near stromal compartment." (PMID 27463005, 2016). "Although innate immune mechanisms impact on B-lymphoma in pre-clinical models, it is clear that inactivation of CD4+ and CD8+ T cells specific for tumor-expressed antigens also occurs." (PMID 26082776, 2015). "Foxp3 + CD4+, CD4+ and CD8+ T cells in tumor stroma and islets were evaluated immunohistochemically." (PMID 26604855, 2015). "In this view, it has been shown that type-1 polarized DCs drive Th1-type immune responses that have the potential to mediate tumor therapy through multiple effectors, such as CD8+ CTLs and Th1-skewed CD4+ T helper cells." (PMID 25815345, 2015). "CD8+ T cells from CD4-cre x IKKβfl/fl mice had dramatically reduced IFN-γ and TNF-α production in response to tumor cell re-stimulation." (PMID 25648675, 2015). "Characterization of tumor-infiltrating CXCR5+CD45RA−CD4+ T cells in 12 pairs of matched tumor and para-tumor tissues showed that the population of CXCR5+CD45RA− cells among CD4+ T cells was higher in tumor tissues than in para-tumor tissues (P = 0.012)." (PMID 26517519, 2015). "We observed consistent trends as shown in the absolute numbers that relative cell numbers of CD4+ and CD8+ TILs were also significantly increased in both 4T1 and E0771 mouse models during the course of tumor development." (PMID 25968569, 2015). "Some studies showed that the ratio between tumor infiltrating CD8+T cells and Foxp3+CD4+ T cells gives prognostic/predictive information than either parameter alone." (PMID 26604855, 2015). "When used as vaccines in both prophylactic and pre-established tumor settings, the IL2-containing TEX were more effective than unmodified TEX or TEX mixed with IL2; CD4+, CD8+, and NK cells were all involved in the anti-tumor immunity." (PMID 26694473, 2015). "It is noteworthy that the decreased CD4+/CD8+ ratio in the tumor tissues is accompanied by increased frequency of CD8+ T cells while in the dLN, this decline is coincided with decreased frequency of CD4+ cells." (PMID 25605488, 2015). "Parallel presentation of antigens both in the context of MHC class I and II molecules contributes to the stronger overall anti-tumor response and long-term immunological memory of CD8+ T cells via CD4+ Th cells." (PMID 25801067, 2015). "GR-1/CD11b-myeloid cells, CD4, MHCII, FOXP3 and vitamin D receptor (VDR)-positive Treg cells were diminished in the tumor microenvironment surrounding microscopic BCCs." (PMID 26413810, 2015). "The fraction of CD4 T cells secreting IFN-γ was found to be significantly higher (p<0.05) in the spleens of NCF1*/+ mice and showed a similar trend at the tumor site." (PMID 26076008, 2015). "In contrast, splenocytes of non-tumor bearing mice contained approximately 2–5% of CD8 and CD4 cells that expressed PD1; and 1–3% that expressed LAG3 (PD1-no tm and LAG3-no tm)." (PMID 26318293, 2015).